IL17A (interleukin 17A)
Diseases named in the same sentence as IL17A in open-access papers (continued):
Sharing a sentence is not in itself a finding about the gene and the disease.
colitis (1,058 papers, 2007 to 2026). Inflammation of the colon. "In contrast, hFcγR mice given IgG from patients with colitis developed colon inflammation marked by a significant increase in submucosal lymphocyte infiltration, goblet cell loss, and circulating cytokines, including IL-1β, IL-17a, and IL-22." (PMID 42282671, 2026). "In contrast, mice recovered from DSS colitis exhibited persistent epithelial barrier defects, chronic colonic neutrophilia, and heightened susceptibility to CR infection despite elevated IL-17A." (PMID 42269772, 2026). "As a result, treatment with IL-17A inhibitors is linked to new-onset and exacerbations of inflammatory bowel disease and colitis." (PMID 40821838, 2025). "For example, adoptive transfer of IL-17A-deficient naïve CD4+ T cells to mice with recombination activating gene-1 deficiency results in more severe colitis with higher expression of genes encoding Th1-type cytokines in colon tissue." (PMID 40565877, 2025). "A previous study presented at European Crohn’s and Colitis Organization (ECCO) congress in 2022 suggested that high levels of IL17A-expressing T cells before treatment was associated with failure to achieve response upon TOF treatment." (PMID 39971758, 2025). "Itch deficiency resulted in spontaneous dermatitis and colitis, which was associated with elevated IL-17A expression." (PMID 40821838, 2025). "IL-17F deficiency resulted in reduced pathology of DSS-induced colitis in mice, whereas IL-17A deficiency was associated with more severe disease." (PMID 39354587, 2024). "We isolated lymphocytes from the livers of these mice and found increased frequencies of Foxp3+ Treg in Mdr2-deficient mice upon acute DSS colitis induction and comparable frequencies of IFNγ+ and IL-17A+ CD4+ T cells." (PMID 38510236, 2024). "Inflammatory responses in models such as the DSS-induced colitis model and Il10−/− mice are exacerbated upon inhibition or deficiency of IL-17A, suggesting a pivotal role for IL-17A in maintaining the integrity of the gut barrier." (PMID 39379604, 2024). "Our case observations underscore the risk of colitis, including both autoimmune and potentially infectious forms, in patients undergoing IL-17A-inhibitor therapy." (PMID 38060157, 2024). "Under similar conditions, orally injecting axenic Blastocystis ST7 into DSS-induced colitis mice exacerbated the severity of colitis by increasing the proportion of pathogenic bacteria and inducing pro-inflammatory IL-17A and TNF-α-producing CD4+ T cells." (PMID 38087868, 2024). "IL-17A and IL-17F have contrasting roles in colitis models, with IL-17A suppression causing excessive inflammation and IL-17F having protective roles." (PMID 39364475, 2024). "Nevertheless, discontinuation of IL-17 inhibitors has reportedly lead to a substantial improvement of symptoms among patients with IL-17A inhibitor-associated colitis." (PMID 38060157, 2024). "Adoptive transfer of T cells deficient in Th17-associated cytokines (IL-17A, IL-17F, and IL-22) into Rag1 knockout mice induced severe colitis comparable to that induced by wild-type cells." (PMID 37239894, 2023). "Conversely, prior ST7 infection exacerbated the severity of colitis by increasing the proportion of pathogenic bacteria and inducing pro-inflammatory IL-17A and TNF-α-producing CD4+ T cells." (PMID 36793854, 2023). "It has been demonstrated that excessive ILC3 activation appears to aggravate experimental colitis by causing the release of IL-17A and IL-22 and an increase in neutrophil infiltration and tissue destruction in animal colitis models." (PMID 36825081, 2023). "Quantifying total CD8+ T cells in the tumors of colitis mice, the numbers of stem-like subset reduced significantly, associating with the IL-17A generation." (PMID 37605139, 2023). "TIGIT deficiency protects mice from DSS-induced colitis by reducing IL-17A–producing CD69+CD103− CD4+ TRM cells." (PMID 35844584, 2022).
colitis (continued). "The inhibition of IL17A by antibodies or an IL17A deficiency can also induce and impair colitis as reported in both mouse and human studies." (PMID 36139354, 2022). "The inhibition of IL-17A production in the DKO mice prevented the development of colitis (loss of body weight, and shorten LILP length, and epithelial hyperplasia) in Rap1KO mice." (PMID 35246619, 2022). "CD69+CD103− CD4+ TRM cells were the major source of interleukin-17A (IL-17A) production in the colon and TIGIT deficiency protected mice from induction of experimental colitis by reducing IL-17A–producing CD69+CD103− CD4+ TRM cells." (PMID 35844584, 2022). "Here, we report that TAGAP-deficient mice are susceptible to DSS-induced colitis, and this is due to significantly increased abundance of IL-17A-and IFN-γ-producing colitogenic CD4+ T cells in the gut." (PMID 36704549, 2022). "In contrast, mitigation of IL-17A with anti–IL-17A neutralizing antibody attenuated colitis in Klf5-deficient mice." (PMID 35393949, 2022). "Taken together, these results demonstrated that colitis in TAM-treated Klf5ΔIND mice exhibited a strong Th17 phenotype that was associated with significant increases in IL-17A and IL-22 levels." (PMID 35393949, 2022). "The finding that blocking IL-17A prevented development of colitis in TAM-treated Klf5ΔIND mice implicates a causative role of IL-17A in the pathogenesis of colitis in these mice." (PMID 35393949, 2022). "Previous studies have reported that colitis is associated with an increase in IL-17A subunit levels, while IL-17F subunit expression is inversely correlated with gut inflammation, which subsequently prompts neutrophil recruitment into the ileum." (PMID 35466218, 2022). "Cytokines associated with colitis inflammation (IL-1β, IL-6, and IL-17A) are significantly inhibited after treatment with M2b macrophage exosomes." (PMID 34683937, 2021). "Meanwhile, in vivo, the MALT1 deficiency colitis mouse model displayed a reduction of the Th17 cell amount and IL‐17A (Th17 cell secreted cytokines)." (PMID 34273195, 2021). "Using mouse models of EAE and colitis we show that loss of RORα affected the expression of IL-17A, RORγt, as well as the frequency of CD25+Foxp3+ Tregs in vivo." (PMID 33397953, 2021). "Colitis is seen at 6 weeks age and increased Il-23p19 expression occurred at the start of colitis associated with increased Il-17A, next to Il-1, Il-6, and Tnf-α expression." (PMID 34267743, 2021). "In previous work, we identified liposomes containing the synthetic TLR ligands GLA and 3M-052 as a promising adjuvant formulation to promote antigen-specific IFNγ/IL-17A-associated immunogenicity and protective efficacy in the amebic colitis mouse model." (PMID 34248966, 2021). "Experiments in mouse colitis models have linked IL-23-responsive NCR− ILC3s to the development IBD through the production of IL-17A, IL-22, and IFN-γ." (PMID 34299236, 2021). "Exosomes from M2b macrophages were found to significantly reduce the severity of dextran sulfate sodium (DDS)-induced colitis in mice and inhibit the expression of key cytokines associated with colitis (IL-1, IL-6, and IL-17A)." (PMID 32411539, 2020). "As consequence, chemically-induced colitis was milder in mice deficient of IL-17F than that of IL-17A-deficient or wild type mice." (PMID 33244315, 2020). "To confirm a causal relationship between IL-17 and colitis, we administered a neutralizing Ab specifically directed against IL-17A to CD4CreTTPf/f mice fed DSS-water and then closely monitored their body weights." (PMID 32922402, 2020). "In mouse models, the constitutive expression of IL-17RC in intestinal epithelial cells explains the more pathogenic effects of IL-17F than IL-17A on microbiota during colitis." (PMID 33244315, 2020). "In conclusion, TGF-β-signaling in Th17 cells promotes IL-17A+IL-22− and IL-17A+IL-22+ T cells, and tumorigenesis during colitis-associated colon cancer in a mouse model." (PMID 32451418, 2020).
colitis (continued). "In vivo, effector functions were compromised since adoptive transfer of NCOR1-deficient CD4+ T cells resulted in attenuated colitis due to lower frequencies of IFNγ+ and IFNγ+IL-17A+ Th cells and overall reduced CD4+ T cell numbers." (PMID 32318068, 2020). "Several studies have shown the Treg involvement in colorectal tumorigenesis, e.g. IL-6 and IL-10 both enhanced tumorigenesis in colitis-associated cancer models, whereas blockade of IL17A inhibited tumor growth." (PMID 32677955, 2020). "In a colitis model caused by dextran sulfate sodium, IL-17A deficiency enhanced colitis, whereas IL-17F deficiency reduced colitis." (PMID 31447673, 2019). "SF68 did not cause pathological inflammation and increases of colonic cytokine expression, whereas UC-derived strain IB44a caused pathological colitis and increased expression of Tnf, Il12b, and Il17a." (PMID 31767028, 2019). "A recent review by Hohenberger speaks to the association of IL-17 inhibition with colitis exacerbation, and collating murine evidence with clinical trial data, IL-17A inhibition in the setting of intestinal inflammation further exacerbates disease." (PMID 31488067, 2019). "Consistently, we found that the recipient mice transferred with Foxp1-deficient iTreg cells developed more severe colitis, indicated by the greater body weight loss and more IFNγ- or IL-17A–producing T cells in the colons." (PMID 31125332, 2019). "Accordingly, inhibition of IL-23 in mice caused a significant decrease in IL-17A levels and IL-17A-mediated immunopathology such as experimental autoimmune encephalomyelitis and spontaneous colitis in Winnie mice." (PMID 30038617, 2018). "Insights in mechanisms underlying the protective capacity of IL-17A have recently been delineated: during DSS-colitis IL-17A-dependent regulation of tight junctions can limit excessive intestinal permeability and therefore promote barrier integrity." (PMID 29124320, 2018). "In vivo, Th17 cells lacking Ndfip1 were more likely than their WT counterparts to maintain lineage commitment, based on production of IL-17A, were much more likely to co-produce other pathogenic cytokines, and caused more severe colitis." (PMID 28051111, 2017). "For instance, it has been implicated the neutralization of IL-17A significantly increases the intestinal tissue damage in dextran sodium sulfate (DSS) induced murine model of colitis." (PMID 29375374, 2017). "In inflammation induced mouse models of CRC it was shown that IL-17A deficient mice showed milder colitis, fewer and smaller tumors and expressed reduced levels of IL-6 and TNF." (PMID 28881611, 2017). "IFN-gamma and IL17A co-expression is thought to identify pathogenic CD4+ T cells in mouse colitis models, so we assessed their co-expression in E coli−reactive memory CD4+ T cells." (PMID 28782508, 2017). "Taking the DSS-induced colitis mice models, for example, IL-17 knockout mice exhibited more severe colitis, whereas IL-17F deficiency mice showed moderated colitis, which suggests completely adverse functions between Il-17A and IL-17F." (PMID 28831399, 2017). "Inflammation-associated mouse models of colon cancer show that IL-17A-/- mice exhibit milder sign of colitis and tumor growth and reduced levels of the pro-inflammatory cytokines IL-6 and TNF." (PMID 28881611, 2017). "To confirm that IL-17A/IL-22 produced by CD4+ T cells are indeed pathogenic factors in Tbx21−/− driven T cell transfer colitis, we stimulated intestinal epithelial cells with supernatant of IL-23-activated WT and Tbx21−/− T cells." (PMID 27193261, 2016). "It has been reported that IL-17 antibody in the progress of acute colitis amplified the colon inflammation although IL-17A deficiency was found to be able to ameliorate colitis in mice." (PMID 26728323, 2016). "Th17 cytokines including IL-17A are generally linked to severity of colitis but also induce protective regulatory mechanisms in epithelial cells." (PMID 25379804, 2014).
colitis (continued). "Another study demonstrated that adoptive transfer of IL-17A-deficient naïve CD4+ T cells or transfer of IL-17 receptor-deficient T cells to recipient immunedeficient mice induces severe colitis, suggesting that IL-17 exerts a protective effect on T cells." (PMID 23956763, 2013). "The contrasting effects of IL-17F and IL-17A have also been observed in intestinal inflammation: IL-17F deficiency reduced while IL-17A deficiency exacerbated DSS induced colitis." (PMID 22509371, 2012). "In this model, IL-21-deficient mice developed a less severe colitis than wild-type mice, characterized by reduced mucosal damage, reduced infiltration of T cells, and diminished production of IL-6 and IL-17A." (PMID 23109839, 2012). "IL-21-deficient mice are largely protected against DSS- and TNBS-colitis, and this protection is associated with a marked decrease in IL-17A and IL-17F, thus confirming the key role of IL-21 in sustaining Th17 immunity." (PMID 22082127, 2011). "For example, there is evidence that IL-17A-knockout mice are more susceptible than control wild-type mice to developing colitis induced by oral administration of dextran sulfate sodium (DSS)." (PMID 22082127, 2011). "We also assessed the expression of genes encoding colitis-associated cytokines that influence susceptibility to C. rodentium infection, including IL-17A and IL17F, IL-22, and IL-23." (PMID 20485566, 2010). "Targeting IL-17A may offer a therapeutic strategy for mitigating colitis-associated inflammation in IBD." (PMID 40995471, 2025). "Using a mouse model of HFD + trinitrobenzene sulfonic acid (TNBS)-induced colitis, dietary n-3 PUFAs have been shown to reduce colitis-associated disease severity and colonic mRNA expression of cytokines (IL-6, IL-17A, IL-17F, IL-21, IL-23, and IFNγ) versus corn oil in control HFD mice." (PMID 40219010, 2025). "Notably, Th17-associated IL-17A positively correlated with intestinal pro-inflammatory mediators, emphasizing the role of Th17 cells in driving colitis." (PMID 40298818, 2025). "A somehow different scenario emerges from studies in Rag-deficient mice after infection with Helicobacter hepaticus, in which the development of IL-23-dependent colitis is associated with enhanced production of pathogenic IL-17A and IFN-γ by NKp46-negative ILC3s." (PMID 41194916, 2025). "This coordinated upregulation of IL-9 and IL-17A may indicate a proangiogenic, early inflammatory state favoring tumor initiation, as suggested in models of colitis-associated CRC." (PMID 41425582, 2025). "Consequently, the pathogenic potential of IL-17A/F in exacerbating colitis has prompted phase 2 studies employing anti-IL-17A or anti-IL-17RA antibodies in the treatment of CD." (PMID 39379604, 2024). "However, IL-17F plays the opposite role from IL-17A and protects mice from colitis-associated colorectal cancer (CAC) induction." (PMID 39906741, 2024). "Increased expression of IL17a was also observed in the spontaneous TCRα‐deficient model of colitis." (PMID 38992956, 2024). "Interestingly, the functional depletion of both IL-17A and IL-22 exacerbated colitis but had minimal effect on weight loss." (PMID 39462273, 2024). "Therefore, the potential risk of IL-17A-inhibitors causing colitis is being discussed, especially as the underlying pathophysiological mechanisms are unclear." (PMID 38060157, 2024). "Notably, the density of proliferative Ki67+CD8+ T cells reduced more profoundly in the tumor bed of colitis mice than in that of normal mice, associated with IL-17A elevation." (PMID 37605139, 2023). "Based on flow cytometry, colitis‐associated Th17 cells are the target of L. intestinalis, which is supported by the lack of protective effects of L. intestinalis in T cell‐null Rag1−/− mice or upon anti‐IL‐17‐A antibody‐treated mice." (PMID 37983567, 2023). "Neutralization of IL-17A by antibody attenuates colitis in Klf5-deficient mice." (PMID 35393949, 2022).
colitis (continued). "They observed that the increased colitis was associated with increased levels of Th17 and Th1 cells, as well as interleukin 17 A (IL-17A) and interferon-gamma (IFN-γ), in the colonic mucosa of mice that have experimentally induced periodontitis when compared to control animals." (PMID 35628390, 2022). "While the transfer of Ihh HET CD4+ T cells potently induced colitis, transfer of Ihh KO CD4+ T cells showed strongly diminished colitis indicated by reduced weight loss, reduced colon thickening/shortening and reduced mucosal infiltration of T cells expressing IL-17a, IL-22 and IFNγ in the colon." (PMID 35835905, 2022). "Paradoxically, although one study had demonstrated that IL-17A-deficiency in prototypical Th1-type C57BL/6 mice reduced DSS colitis, a separate study using IL-17A- and IL-17F-deficient mice demonstrated a deleterious role for IL-17F in the development of disease." (PMID 36012618, 2022). "IL-23 deficient mice were unable to express IL-17A during S. Typhimurium-induced colitis." (PMID 34943999, 2021). "Moreover, IL-17A and IL-17RA inhibition have been associated with the breakdown of the intestinal epithelial barrier and exacerbated colitis in Helicobacter bilis-infected mice." (PMID 33654214, 2021). "Indeed, Il17a−/− mice demonstrated more severe inflammation in DSS-induced colitis compared to controls, which was associated with increased intestinal permeability." (PMID 33562334, 2021). "A loss of the IL-23 receptor led to lower IL-17A expression during DSS-induced colitis." (PMID 33202783, 2020). "Other investigators also showed that HSD causes IL-17A-dependent colon inflammation." (PMID 33126615, 2020). "In addition, key cytokines associated with colitis (IL-1β, IL-6, and IL-17A) were significantly suppressed, following treatment with M2b macrophage exosomes." (PMID 31749791, 2019). "IL-17A deficiency aggravates cholangitis but ameliorates colitis." (PMID 29868034, 2018). "Likewise, IL-17F has been reported to play a pathogenic role in colitis development with either redundant or different functions compared to IL-17A." (PMID 29124320, 2018). "Furthermore, transfer of IL-17A- or IL-17RA-deficient Th cells into RAG recipient mice lead to an enhanced colitis-like wasting disease." (PMID 29910812, 2018). "In particular, a recent study has implicated that IL-17A can promote epithelial barrier function by regulating the tight junction protein occluding through the IL-17R adaptor protein Act-1 on epithelial cells in DSS-induced colitis model." (PMID 29375374, 2017). "As proinflammatory cytokines IFN-γ, IL-17A and granulocyte–macrophage colony-stimulating factor have been implicated in playing important roles in the development and pathogenesis of colitis, we investigated their production by CD4+ T cells from Bcl-3TOE mice compared with controls." (PMID 28452361, 2017). "Furthermore, another study demonstrated that adoptive transfer of IL-17A deficient naıve CD4+ T cells or transfer of IL-17 receptor deficient T cells to immuno-deficient recipients provokes severe colitis." (PMID 28584821, 2017). "Our in vitro experiments suggest that IL-17A and IL-22 synergise to promote intestinal epithelial cell responses, which may in part explain the efficacy of blocking IL-17A or IL-22 in colitis induced by T-bet-deficient T cells." (PMID 27193261, 2016). "To test which effector cytokines were required for colitis induced by T-bet-deficient T cells, we transferred cohorts of Rag1−/− recipients with WT or Tbx21−/− T cells and administered neutralizing antibodies to IL-17A or IL-22." (PMID 27193261, 2016). "The pathogenic role of IL-22 in CD40-triggered colitis may depend on the presence of microbial factors that also influence IL-17A production in the intestine." (PMID 26780670, 2016).